SNX6 (sorting nexin 6)
Description:
Involved in several stages of intracellular trafficking. Interacts with membranes phosphatidylinositol 3,4-bisphosphate and/or phosphatidylinositol 4,5-bisphosphate (Probable). Acts in part as component of the retromer membrane-deforming SNX-BAR subcomplex. The SNX-BAR retromer mediates retrograde transport of cargo proteins from endosomes to the trans-Golgi network (TGN) and is involved in endosome-to-plasma membrane transport for cargo protein recycling. The SNX-BAR subcomplex functions to deform the donor membrane into a tubular profile called endosome-to-TGN transport carrier (ETC) (Probable). Does not have in vitro vesicle-to-membrane remodeling activity. Involved in retrograde endosome- to-TGN transport of lysosomal enzyme receptor IGF2R. May function as link between transport vesicles and dynactin (Probable). Negatively regulates retrograde transport of BACE1 from the cell surface to the trans-Golgi network. Involved in E-cadherin sorting and degradation; inhibits PIP5K1C isoform 3-mediated E-cadherin degradation. In association with GIT1 involved in EGFR degradation. Promotes lysosomal degradation of CDKN1B (By similarity). May contribute to transcription regulation (Probable).
Synonyms: MSTP010; TFAF2
Tractability: Antibody: UniProt places it where antibodies can reach, with high confidence. PROTAC: ubiquitination databases record sites on it; its protein half-life has been measured.
Gene: Protein-coding gene on chromosome 14 (34,561,093 to 34,630,177, reverse strand). Ensembl gene ENSG00000129515.
Subcellular location: Early endosome; Early endosome membrane; Cytoplasmic vesicle; Cytoplasm; Nucleus
Subcellular location (Human Protein Atlas): Endosomes; Lysosomes
Gene Ontology:
Molecular function: dynactin binding; protein binding; protein homodimerization activity; phosphatidylinositol binding; type I transforming growth factor beta receptor binding
Biological process: cellular response to amyloid-beta; intracellular protein transport; negative regulation of DNA-templated transcription; negative regulation of neuron apoptotic process; negative regulation of transforming growth factor beta receptor signaling pathway; regulation of histamine secretion by mast cell; retrograde transport, endosome to Golgi; negative regulation of epidermal growth factor-activated receptor activity; regulation of macroautophagy; cellular response to epidermal growth factor stimulus; endosomal transport; intercellular transport; regulation of postsynaptic membrane neurotransmitter receptor levels
Cellular component: cytoplasm; cytoplasmic vesicle; early endosome; early endosome membrane; endosome; lysosome; nucleus; retromer complex; retromer, tubulation complex; tubular endosome; cytosol; glutamatergic synapse; postsynaptic early endosome
Genetic constraint (gnomAD): Loss-of-function variants: 14 observed, 26.98 expected, observed/expected ratio (o/e) 0.52, 90% interval 0.34 to 0.81. The upper end of that interval is the gene's LOEUF score, 0.81, which puts it in group 3 of 6, group 1 being the genes least tolerant of losing a copy. Missense variants: 198 observed, 234.09 expected, observed/expected ratio (o/e) 0.85, 90% interval 0.75 to 0.95. Synonymous variants: 99 observed, 89.06 expected, observed/expected ratio (o/e) 1.11, 90% interval 0.94 to 1.31.
Homologues: Orthologues: chimpanzee SNX6 (99% identical), dog SNX6 (99% identical), guinea pig SNX6 (99% identical), macaque SNX6 (99% identical), mouse Snx6 (99% identical), pig SNX6 (99% identical), rabbit SNX6 (99% identical), rat Snx6 (99% identical), tropical clawed frog snx6 (93% identical), zebrafish snx6 (93% identical). Paralogues in human: SNX32 (67% identical), SNX5 (64% identical), SNX2 (20% identical), SNX1 (20% identical), SNX18 (18% identical), SNX4 (17% identical), SNX7 (17% identical), SNX8 (17% identical), SNX30 (17% identical), SNX33 (15% identical), SNX9 (15% identical), SNX11 (11% identical), and 3 more.
Diseases named in the same sentence as SNX6 in open-access papers:
SNX6 is named in the same sentence as 15 diseases in open-access papers, as found by Europe PMC text mining. Sharing a sentence is not in itself a finding about the gene and the disease. The quoted sentences say what the papers report.
chlamydial infection (2 papers, 2019 to 2025). "Given that IncD and IncE are expressed on the IM during persistence, it is likely that SNX6 and CERT are traffickings to the IM as they would during a normal chlamydial infection and that the differences seen here are not biologically significant." (PMID 39804088, 2025).
pancreatic cancer (2 papers, 2022). "SNX6 has been reported in pancreatic cancer and implicated in regulating EMT and invasiveness of cancer cells." (PMID 36612066, 2022). "Complementing these observations, SNX6 was highly expressed in pancreatic cancer patients and correlated with poor prognosis." (PMID 36612066, 2022). "In pancreatic cancer cells, SNX6 overexpression has been witnessed to maintain mesenchymal properties of tumor cells, contributing to metastasis, while SNX6 silencing inhibited the EMT process induced by TGF-β, suggesting engagement of SNX6 with metastasis of pancreatic cancer." (PMID 35715463, 2022).
breast carcinoma (1 paper, 2022). "As also institutional structure of retromer, SNX6 has been reported to enhance the core effect of breast cancer transcription in a dose-dependent manner, that is suppressing transcription in breast cancer." (PMID 35715463, 2022).
colon cancer (1 paper, 2025). "Some members, such as SNX1, SNX6, and SNX27, have oncogenic properties, promoting proliferation and metastasis by activating the TGF-β signaling pathway and recycling cancer-associated proteins in gastric, pancreatic, and colon cancer, respectively." (PMID 40810725, 2025).
listeriosis (1 paper, 2023). A bacterial infection caused by Listeria monocytogenes. "Furthermore, Listeria monocytogenes, the causative agent of listeriosis, secretes the virulence factor Lmo1656 that binds SNX6 to subvert its function during early stages of oral listeriosis." (PMID 37089068, 2023).
osteosarcoma (1 paper, 2023). A usually aggressive malignant bone-forming mesenchymal neoplasm, predominantly affecting adolescents and young adults. "To this end, we performed double knockout (KO) of SNX1 and SNX2 (SNX1-2), and SNX5 and SNX6 (SNX5-6), in the human osteosarcoma cell line HT1080." (PMID 37322239, 2023).
ZIKV infection (1 paper, 2023). "Increased mRNA expression levels of ISG15 upon Snx6 and/or Snx9 knockdown during ZIKV infection were observed, suggesting that disruption of MDV formation during ZIKV infection affects the host antiviral response in JEG-3 cells." (PMID 37781396, 2023).
infection (5 papers, 2010 to 2023). The state of being infected such as from the introduction of a foreign agent such as serum, vaccine, antigenic substance or organism. "The stability ranking at different developmental stages associated with infection of PWN was as the following: TER > RPL7 > RPS5 > Zdhhc15 > EF1-γ > RPL18 > Tmub1 > SNX6 > ATPase > TFAM > α-TUB > EIF > TPI > COX7." (PMID 35547586, 2022). "Increased expression of CT813 also reduced the recruitment of sorting nexin-6 (SNX6), a eukaryotic protein binding partner of IncE, to the inclusion during infection." (PMID 33875478, 2021). "This colocalization depends on Lmo1656, and RNAi of SNX6 impairs infection in infected tissue culture cells, suggesting that SNX6 is utilized by Lm during infection." (PMID 29666193, 2018). "Therefore, we further investigated the importance of MDVs during PRV infection in JEG-3 cells via Snx6- and Snx9-specific siRNA transfection individually or in combination prior to infection." (PMID 37781396, 2023). "For different developmental stages associated with infection of PWN and pupae treated with PWN, two conditions had similar results that RPS5, RPL18, and RPL7 were identified as the most stable genes, but α-TUB, COX7, EIF, and SNX6 were poor stable genes." (PMID 35547586, 2022). "We then sought to determine the role of SNX6 during infection." (PMID 29666193, 2018). "SNX6 colocalizes with WT Lm during the early steps of infection." (PMID 29666193, 2018). "Because Lmo1656 contributes to early infection of certain types of cultured cells, we first assessed whether the subcellular localization of its putative host target, SNX6, is affected during infection." (PMID 29666193, 2018). "The reduced expression of SopB in the presence of H2O2 and at later time points of infection in macrophages and in the spleen in our study is consistent with the notion that SopB negatively regulates expression of sorting nexin 6 (SNX6), a protein involved in intracellular transport." (PMID 20529336, 2010). "In contrast, SNX6 is required for productive infection in epithelial cells, and lmo1656 deletion does not alter bacterial growth in macrophages." (PMID 29666193, 2018).
cancer (4 papers, 2016 to 2025). A tumor composed of atypical neoplastic, often pleomorphic cells that invade other tissues. "Reflecting the pleiotropic functions of the vitamin D/PTH axis, other potential candidate genes were also implicated immune/inflammatory processes (NKX2, PSMA6, SNX6) as well as cancer (NKX2, NKX3, PAX9)." (PMID 27579147, 2016). "Loss of SNX6 resulted in the downregulation of N-cadherin and ZEB1, a mesenchymal gene and transcriptional factor, respectively, whereas upregulating E-cadherin resulted in the inhibition of the migration and invasive capacity of the cancer cells." (PMID 36612066, 2022).
neurological diseases (1 paper, 2023). "Our work provides a new information on the role of SNX5 and SNX6 in the molecular regulation of retrograde membrane trafficking and vesicular membrane targeting in monoamine neurotransmission and neurological diseases." (PMID 37964759, 2023).
SNX6 also shares sentences with these, for which no sentence is quoted: tumor (4 papers); Anxiety (1); diabetes (1); holoprosencephaly (1); neuroblastoma (1).